FGFR3 (fibroblast growth factor receptor 3)
Diseases named in the same sentence as FGFR3 in open-access papers (continued):
Sharing a sentence is not in itself a finding about the gene and the disease.
cancer (continued). "This study underscores the potential of natural compound-derived FGFR3 inhibitors to anti-cancer and sensitize Ceritinib." (PMID 38919748, 2024). "The FGFR3 seems to have diverse roles as its expression is upregulated in some cancers and downregulated in others." (PMID 38635549, 2024). "Jinget al. reported that after FGFR3 is inhibited, obvious upregulation of PD-L1 expression is observed, while cancer cells with high FGFR3 expression exhibit low PD-L1 expression." (PMID 38826132, 2024). "Among others, we found that targeted treatment with JAK3, HER2, or FGFR3 inhibitors showed anti-cancer effects in individual brain metastasis cultures." (PMID 38985431, 2024). "Low-grade carcinomas show FGFR3 alterations in 80% of cases, have a high recurrence rate, and have non-aggressive behavior." (PMID 39064555, 2024). "We used the R/ATA system to identify Pa as a factor that can reduce FGFR3 protein abundance by directly shortening its half-life, which attenuates FGFR3 downstream signaling in both cancer cells and chondrocytes." (PMID 37824212, 2023). "Disrupter drugs such as PD173074 and bemarituzumab are the potent and selective blockers of FGFR1 and FGFR3, and FGFR2b, respectively, and are used to treat different cancers." (PMID 37108717, 2023). "In the TCGA test group, ERPI involved in chemokine receptors binds chemokines, MHC class II antigen presentation, apoptotic cleavage of cell adhesion proteins, and signaling by FGFR3 fusions in cancer pathways." (PMID 36968596, 2023). "Frequency of patients with FGFR3 fusion gene across cancer types consisting of our cohort and two public datasets (cBioPortal and C‐CAT)." (PMID 37537783, 2023). "the VM_Score was also associated with low sensitivity to antiangiogenic and targeted therapies that target the FGFR3, β-catenin, and PPAR-γ pathways but are associated with high sensitivity to cancer immunotherapy, neoadjuvant chemotherapy, and radiotherapy." (PMID 37197406, 2023). "We demonstrated that Pa reduced FGFR3 protein abundance by shortening its half-life, which subsequently attenuated FGFR3 downstream signaling in both cancer cells and chondrocytes." (PMID 37824212, 2023). "Studies of FGFR3 in BCa are fairly well developed; in fact, there are clinical trials examining FGFR3 inhibitors in cancer treatment." (PMID 36674480, 2023). "Consistently, Pa effectively suppresses FGFR3 signaling–induced clinical phenotypes in cancer cells and femurs." (PMID 37824212, 2023). "Researchers aimed to assess the overall response rate (ORR) of pemigatinib monotherapy in patients with advanced or inoperable cancer and appropriate FGFR3 aberrations." (PMID 35326568, 2022). "K–M analysis indicated that the high FGFR3 expression group showed marginally significantly higher cancer-specific survival (CSS) rates than the low FGFR3 expression group (p = 0.059)." (PMID 35563543, 2022). "FGFR3 fusions were common in lung and urinary cancers, but were also found in a wide variety of cancer types, particularly cancers of the gastrointestinal tract." (PMID 36369474, 2022). "For example, we identified “Signaling by FGFR3 point mutants in cancer” as potential targets for treatment of the SC4 subtype." (PMID 35439935, 2022). "Alterations affecting FGFR3 signaling were detected more frequently in the urinary bladder than in any other cancer type." (PMID 36361996, 2022). "We observed similar cancer-specific H3K4me3-BDs associated with hijacking of super-enhancers of other common oncogenes in B cell (MAF, MYC, and FGFR3/NSD2) and T cell malignancies (LMO2, TLX3, and TAL1)." (PMID 34933939, 2022).
cancer (continued). "Because FGFR3 is a well-known cancer-related gene, we further compared its alteration profile between the HDGC and TCGA STAD cohorts." (PMID 36484990, 2022). "The resulting CNV profiles of established cell lines showed concordance with previously reported data and highlight several gains and losses of cancer-related genes such as FGFR3 and GNAS." (PMID 35887203, 2022). "Multiple drugs that co-inhibit FGFR3 along with other plasma membrane receptors are being studied as cancer therapeutics." (PMID 33920951, 2021). "In cancers, FGFR3-mediating signals are often activated by manifold mechanisms, such as activating receptor mutations, translocations, altered splicing, upregulation of FGFs and/or FGFR3, and defects in negative feedback loops." (PMID 33935756, 2021). "NMIBC generally involves the fibroblast growth factor receptor 3 (FGFR3) mutation, producing cancer with a high recurrence rate but a low risk of progression." (PMID 34822414, 2021). "Screening for the impact of other amplified cancer genes in HEK293 cells also demonstrated that EGFR, AKT2, CCND1, CCNE1, SKP2, and FGFR3 caused both increased abundance of phosphorylated ZFP36/TTP and ARE-post-transcriptional reporter activity." (PMID 34535639, 2021). "The most common cancer types with FGFR3 CNVs were UCS (78.9%), LUSC (69.2%), ESCA (68.7%), OV (66.5%), and TGCT (65.1%)." (PMID 34160364, 2021). "In this work, we used the open comprehensive datasets, covering a total of 10,953 patients with 10,967 samples across 32 TCGA cancer types, to identify the full alteration spectrum of FGFR3." (PMID 34160364, 2021). "These include known factors such as IDH1, as well as previously unreported genes, including four cancer driver genes (FGFR3, PPP6C, MAX, GNAQ)." (PMID 34944895, 2021). "Upregulated expression of FGFR3 was observed in 4 cancer types (OV, TGCT, THYM, and UCS) and downregulated expression of FGFR3 was observed in 2 cancer types (LAML and LGG)." (PMID 34160364, 2021). "In several cancer types amplification accounted for a major proportion of FGFR3 alterations such as OV, ACC, CHOL, PAAD, GBM, and SARC." (PMID 34160364, 2021). "Using FGFR3-overexpressing patient-derived cancer cells, biotin-X-DHPE was introduced and coupled to Streptavidin-coated magnetic beads for use in the solution-phage bio-panning procedure." (PMID 34207911, 2021). "In contrast to FGFR1 amplification and FGFR3 mutation, research has shown that the response to AZD4547 among FGFR2-amplified cancers is strong." (PMID 34639155, 2021). "Meanwhile, we further conducted the survival association analysis regarding alteration status across different cancers to explore the clinical value of the FGFR3 alterations." (PMID 34160364, 2021). "The analysis results showed that FGFR3 expression, methylation, and alteration varied greatly from cancer to cancer." (PMID 34160364, 2021). "In this study, the characteristics of FGFR3 across 32 TCGA cancer types were profiled, which were of critical therapeutic and clinical significance." (PMID 34160364, 2021). "Fibroblast growth factor receptor 3 (FGFR3) alters frequently across various cancer types and is a common therapeutic target in bladder urothelial carcinoma (BLCA) with FGFR3 variants." (PMID 34160364, 2021). "Fibroblast growth factor receptor 3 (FGFR3) is a well-established cancer driver gene in several cancers, and single molecule inhibitors of this gene are used as therapeutic agents." (PMID 34944895, 2021). "Conclusively, our analysis results highlight the important role of FGFR3 in tumorigenesis and provide potential and promising therapeutic targets across different cancers." (PMID 34160364, 2021).
cancer (continued). "We sought to establish if the drug responses observed in the NIH-3T3 model system is also present in cancer cell lines harbouring endogenous FGFR3 molecular alterations." (PMID 32370101, 2020). "Genetic aberrations of FGFR1 are more frequently observed in human cancers (2.86%), followed by alterations in FGFR3 (2.21%), FGFR2 (1.77%), and FGFR4 (1.54%)." (PMID 32962091, 2020). "The most frequent mutation of FGFR3 detected in premalignant vulvar lesions was p.S249C, described previously in VSCC hrHPV(+) (2-14%) and other HPV-associated cancers." (PMID 32664330, 2020). "And in RT-PCR, FGFR3-mRNA expression in cancer tissues was significantly higher than that in adjacent tissues (p < 0.001)." (PMID 33381388, 2020). "Despite low frequencies, therapeutic targeting of FGFR3 represents a potential option for cancers exhibiting oncogenic forms of FGFR3, supported by our data regarding the efficacy of PD173074 in SUM185PE cells." (PMID 31987043, 2020). "We first evaluated the effects of infigratinib in NIH-3T3 cells expressing a selection of the most prevalent activating FGFR3 molecular alterations in cancer." (PMID 32370101, 2020). "The identification of these FGFR3 aberrations in cancer has led to the clinical evaluation of selective Fibroblast Growth Factor Receptor (FGFR) small molecule tyrosine kinase inhibitors (TKIs) in this molecularly defined subset of patients." (PMID 32370101, 2020). "The work presented here supports the evaluation of ABT263 or other Bcl‐XL inhibitors in combination with FGFR inhibition in other FGFR2‐ and FGFR3‐dependent cancers." (PMID 30537101, 2019). "Collectively, these findings show that FGFR3 plays an important role in shaping the T-cell-depleted phenotype in UTUC in a cancer-cell autonomous manner." (PMID 31278255, 2019). "3D185 inhibited FGFR1-, FGFR2-, FGFR3-, and CSF-1R-mediated cancer cell proliferation, with IC50 values ranging from 0.9 to 36.8 nM." (PMID 31438996, 2019). "To evaluate 3D185’ potential advantage of dual targeting FGFR and CSF1R with equal potency, we further used a co-cultured context with FGFR3-driven RT112 cancer cell line and CSF-1-differentiated human macrophages." (PMID 31438996, 2019). "The results confirmed that alterations involving RB1 and NFE2L2 were enriched in basal cancers, whereas alterations involving FGFR3 and KDM6A were enriched in luminal tumors." (PMID 29977169, 2018). "FGFR3 promotes the survival of cancer cells just by stimulating the downstream PI3K/AKT/mTOR pathway." (PMID 29545752, 2018). "What is noteworthy is that as an important step to promote metastasis, EMT process was involved in FGFR3-mediated cancer metastasis by means of regulation of transcription factors, such as Snail." (PMID 29850625, 2018). "Ion AmpliSeq Cancer Hotspot Panel v2 and nCounter Copy Number Variation Assay were used to detect FGFR3 aberrations." (PMID 30064409, 2018). "The K650E/K652E residue in tyrosine kinase domain 2 of FGFR3 (of isoforms IIIB and IIIC respectively) causes constitutive receptor activation and is found in bladder and other cancers." (PMID 29423038, 2018).
cancer (continued). "Taken together, these observations indicate that SCAT7/hnRNPK/YBX1 RNP plays a crucial role in the transcriptional activation of FGFR2 and/or FGFR3 in different cancer models." (PMID 29491376, 2018). "The genomic data for both cancer types reveal a promising druggable target, the fibroblast growth factor receptor 3 (FGFR3)." (PMID 29933636, 2018). "The involvement of FGFR3 in bladder and other cancers has led to the development of a variety of approaches designed to directly block the oncogenic function of FGFR3." (PMID 29423038, 2018). "As expected, fusions in the FGFR kinase family (FGFR2 and FGFR3) are the most frequent 5′-kinase fusions, given their high recurrence in individual cancer types." (PMID 29617662, 2018). "This is of interest because aside from gatekeeper mutations, there is also evidence that FGFR inhibitor resistance can come from a switch to ERBB2/3 signaling (structurally related to EGFR) in models of FGFR3-dependent cancer cell lines." (PMID 28030802, 2017). "Of note, in HCT116, additional mutations in the APC, FGFR3 and STK11 genes have been described in the literature but are not included in the mutations that can be detected by the hotspot cancer panel v2." (PMID 28060956, 2017). "This suggests to us that there is little contribution of altered FGFR3 signalling to mitotic defects observed in FT3-positive cancer cells." (PMID 28855393, 2017). "Similarly, the higher sensitivity to FGFR-inhibitors observed in FGFR3-fusion expressing cancer cells, compared to FGFR3 point mutations, could be better understood by comprehensive analyses and comparison of cellular networks linked to these different FGFR3 aberrations." (PMID 29262532, 2017). "The number of observed mutations at each residue within the intracellular portion of FGFR3 was compiled from several cancer databases (COSMIC, TCGA, ICGC and BioMuta) covering all cancer types (top)." (PMID 26992226, 2016). "FGFR2 and FGFR3 mutations have been identified among 17.6 % of HPV-positive tumors, and both mutations have been described in several cancer types, and are sensitive to FGFR inhibitors." (PMID 27154171, 2016). "FGFR3 have also been discussed as a potential prognostic markers in several cancers, however data remain controversial." (PMID 27154171, 2016). "The expression of FGFR1, FGFR2, and FGFR4 were higher in cancer tissues than in normal tissues, whereas the expression of FGFR3 was higher in normal tissues." (PMID 27154171, 2016). "It has been previously highlighted that a number of cancer mutations, in particular in FGFR2 and FGFR3, have also been described in various developmental syndromes such as bone dysplasia." (PMID 26992226, 2016). "When compared with normal tissues, the expression of FGFR1, FGFR2, and FGFR4 were higher and the expression of FGFR3 was lower in cancer tissues." (PMID 27154171, 2016). "Comparison of positions mutated in bone dysplasia in all FGFRs with those reported for FGFR3 in cancer (bottom) highlighted common residues including I538, N540, K650 and R669." (PMID 26992226, 2016). "Positions mutated in FGFR3 in this type of dysplasia included not only one of the hotspots observed in FGFR3 in cancer (K650) but also the N540 hotspot position." (PMID 26992226, 2016).
cancer (continued). "HER2, EGFR, FGFR2 and FGFR3 missense substitutions were observed in 10(3.5%), 1(0.4%), 5(1.8%) and 2(0.7%) of the cancers, respectively." (PMID 25669975, 2015). "The authors found FGFR-3 expression in normal mucosa as well as its significant expression in carcinoma, predominantly in the basal layers." (PMID 26465941, 2015). "By combining the mutational data in the Catalogue of Somatic Mutations in Cancer (COSMIC) and the spatial information in the Protein Data Bank (PDB), SpacePAC is able to identify novel mutation clusters in many proteins such as FGFR3 and CHRM2." (PMID 24990767, 2014). "When compared, genes with upregulation in FGFR3 mutant cancers had significantly higher expression in the FOXA1 transfected cells (average 1.10±0.2 fold change, p<0.001) than those without change." (PMID 25071007, 2014). "Very few regions of high-level copy number gain were found, an exception being amplification around the CCND1 oncogene on chr11q13.3 and at the FGFR3 locus on chr4p16.3, each in a single cancer (#4121 and #615, respectively)." (PMID 24777035, 2014). "bFGF up-regulates survivin expression in certain cancer cells, and survivin plays an essential role in angiogenesis in tumors by up-regulating bFGF expression, leading to activation of the FGFR3-mediated signaling pathway." (PMID 24467821, 2014). "Genes with increased expression in FGFR3 mutant cancers were significantly closer to FOXA1 binding sites (433,101bp (95%CI=331,878-534,324)) than those without change (837,209bp T Test p<0.001)." (PMID 25071007, 2014). "These deletions contained known cancer genes based on the Sanger Census cancer gene list, including FGFR3, RECQL4, NOTCH1, PTEN, TSC2, and/or ASPSCR1 which suggested their roles as tumor suppressor genes in the development of HCC." (PMID 25469175, 2014). "Whilst mutation of this oncogene occurs most commonly in low-grade non-invasive UCC, FGFR3 upregulation characterises the large chemosensitive sub-group of invasive cancers." (PMID 25071007, 2014). "It seemed that FGFR3 impacted cancer cell clonogenic properties independently of its kinase activity." (PMID 23902722, 2013). "It is important to note that PI3K/Akt pathway is a key regulator of cell growth and survival in many cancers, including FGFR3 regulated cancers." (PMID 23409016, 2013). "This suggests that the mechanism by which gefitinib induces FGFR2 and FGFR3 is likely to be operative in diverse epithelial-derived cancer cell lines." (PMID 21152424, 2010). "Additionally, Erdafitinib is the subject of another phase III trial involving advanced cancer patients with FGFR3 genetic alterations who have exhausted standard treatment options." (PMID 40943615, 2025). "Notably, the FGFR3::TACC3 fusion plays a role in tumorigenesis in various cancers, including bladder, lung, and uterine cervical malignancies, underscoring its broader oncogenic significance." (PMID 40417325, 2025). "Furthermore, Debio 1347, an ATP competitive inhibitor targeting FGFR1-3, is also in phase II trials, highlighting ongoing efforts to enhance treatment options for FGFR3-driven cancers." (PMID 40943615, 2025). "Additionally, a phase II/III clinical trial comparing Rogaratinib, a novel targeted therapy for FGFR3-driven cancers, with chemotherapy has shown comparable efficacy and a favorable safety profile in patients with FGFR3 genetic abnormalities." (PMID 40943615, 2025). "In the mouse model dataset, TPCS cancer cells overexpress the luminal markers Xbp1 and Fgfr3 as well as the basal stem cell markers Itga6 and Cd44, the basal marker Egfr, and the EMT‐related marker Cldn4, suggesting that TPCS are of potential to generate multiple lineages." (PMID 38582099, 2024). "FGFR gene fusions such as FGFR3-TACC3 may trigger cancer development, allowing the activation of FGFR3 tyrosine kinase." (PMID 38255923, 2024).